SLIT2 (slit guidance ligand 2)
Diseases named in the same sentence as SLIT2 in open-access papers (continued):
Sharing a sentence is not in itself a finding about the gene and the disease.
breast carcinoma (continued). "Therefore, we assumed that Slit2/Robo1 axis has effects on breast cancer brain metastasis probably by modulation of PI3K/Akt/β-catenin/MMP-9 signaling." (PMID 26400100, 2015). "Recently, Slit2 was shown to downregulate CXCR4 expression in breast cancer cells." (PMID 23294842, 2013). "Additionally, several studies have demonstrated that SLIT2 inhibits tumor growth and metastasis by a mechanism that involves the regulation of tumor migration, invasion, apoptosis, and growth in breast cancer, fibrosarcoma, and squamous Cell Carcinoma." (PMID 22140553, 2011). "Recently, we identified frequent promoter methylation without somatic mutations of SLIT2 in lung and breast cancers, suggesting similarities between SLIT2 and RASSF1A TSGs." (PMID 14735202, 2004). "Thus having established SLIT2 as a lung and breast cancer suppressor gene, we have now identified frequent SLIT2 hypermethylation in paediatric cancers and in RCC and, recently, in 59% of gliomas." (PMID 14735202, 2004). "Moreover, Slit2 treatment reduced the α-KG-to-succinic acid ratio and changed mitochondrial respiration metabolites in macrophage-derived from healthy human blood that had been treated with breast cancer patient plasma." (PMID 37491279, 2023). "Furthermore, our studies indicate that Slit2 may represent a novel immuno-therapeutic approach against aggressive breast cancer by modulating the metabolism of macrophages." (PMID 34777365, 2021). "Last but not least, delayed onset of EndMT in the lungs of 4T1 breast cancer-bearing mice could also have been associated with other Slit2-independent signaling pathways, such as bFGF-dependent signaling counteracting TGF-β signaling." (PMID 30075800, 2018). "Bioinformatic analysis indicated that FLERT2, SLIT2, VNN1, MAP1B, MYLK, and TUBA1A gene expressions were found to be higher in normal tissue than in tumor tissue of breast cancer patients." (PMID 39596804, 2024). "We have previously shown that Slit2 inhibits chemokine CXCL12-induced chemotaxis and chemoinvasion of breast cancer cells by inhibiting PI3K and MAPK activity." (PMID 34777365, 2021). "The chemokine-mediated signaling pathway is represented by SLIT2 and SLIT3 genes that play a suppressive role in tumor metastasis and are often epigenetically silenced in a wide variety of cancers including breast cancer." (PMID 32679794, 2020). "Collectively, these data strongly suggest that SOX7 activates SPRY1 and SLIT2, but inhibits MTHFD2 and TRIB3 in breast cancer." (PMID 29757932, 2018). "We found that breast cancers with low expression of the crosstalk molecules, Sonic Hedgehog (SHH) or Slit homolog 2 (SLIT2), have significantly shorter relapse-free survivals than those with high expression." (PMID 28440283, 2017). "Furthermore, the mean interval (from diagnosis of breast cancer to brain metastasis) and mean survival (from diagnosis of brain metastasis to death) were both significantly shorter in patients with low expression of Slit2 or Robo1 than the high expression group." (PMID 26400100, 2015). "miR-218 is located within the introns of SLIT2 and SLIT3, whose promoter regions are frequently hypermethylated in cancers, including ovarian cancer, breast cancer, and cervical cancer." (PMID 26610476, 2015). "CXCL12 was reported to activate the migration of human melanoma and breast cancer cells that express CXCR4, ROBO1 and ROBO2, while SLIT2-ROBO interaction was demonstrated to inhibit chemotaxis, chemoinvasion and adhesion of breast cancer cells." (PMID 19114000, 2008). "Furthermore, patients with Basal and Luminal A breast cancer had a positive correlation between the expression of the ESR2 gene and SLIT2, presenting a new possible field to explore as a marker." (PMID 39596804, 2024).
breast carcinoma (continued). "Analyzing databases for paracrine signaling through receptor-ligand pairs, occurring both on luminal and myoepithelial cells, we found that breast cancers with low expression of the crosstalk molecules SHH and SLIT2 resulted in significantly shorter relapse-free survivals." (PMID 28440283, 2017). "In this clinicopathologic study, we found that breast cancer patients with low expression of Slit2 or Robo1 exhibited brain-specific metastasis, but not liver, bone or lung." (PMID 26400100, 2015). "Moreover, low expression of Slit2 or Robo1 in breast cancer patients correlated with poor OS and DFS, suggesting Slit2/Robo1 axis can serve as a prognostic biomarker of breast cancer." (PMID 26400100, 2015). "Additionally, Slit2 blocks cell motility and tumorigenesis by downregulation of CXCR4 in a mammary tumor model." (PMID 26572553, 2015). "In contrast, the activity of breast cancer cells lacking Robo1-expression was rather stimulated by Slit2-expressing fibroblasts, demonstrating that the functional outcome of CAF activity is decided on the level of the malignant cells." (PMID 24734219, 2014). "Notably, our clinical data showed, for the first time, that low expression of Slit2 or Robo1 positively correlated with brain-specific metastasis of breast cancer patients, but not liver, bone or lung metastasis." (PMID 26400100, 2015). "However, until present, there are no convincing reports that suggest whether the Slit2/Robo1 axis has any role in brain metastasis of breast cancer." (PMID 26400100, 2015). "According to a bioinformatic study, the expression of the genes FLRT2, SLIT2, VNN1, MAP1B, MYLK, and TUBA1A was found to be higher in normal tissue than in malignant tissue in patients with breast cancer." (PMID 39596804, 2024). "However, in contrast to breast cancer cells, Slit2N did not have any effect on the downregulation of either CXCR4/CCR5 or CD4 expression, ruling out down-modulation of HIV-1 receptors/co-receptors as a mechanism of action for Slit2." (PMID 23294842, 2013).
lung carcinoma (31 papers, 2004 to 2025). "In a previous study, we identified Slit2-WT and Slit2-ΔE15 splicing variants and demonstrated that Slit2-ΔE15 can inhibit both the proliferation and invasion of lung cancer cells, while Slit2-WT only possesses invasion inhibitory activity." (PMID 41227302, 2025). "About 25% of ROBO1, 25% of ROBO4, and 35% of SLIT2 variants of non-lung cancer dataset were predicted to be "Disease-related" by SNPs&GO." (PMID 33318575, 2020). "Amino acid sequence-based predictions from FATHMM46 using hidden Markov Models revealed 0% of ROBO1, 6% of ROBO4, and 0% of SLIT2 variants of lung cancer dataset to be associated with some form of "cancer"." (PMID 33318575, 2020). "About, 0.4% of ROBO1, 0.8% of ROBO4, and 2% of SLIT2 variants of non-lung cancer dataset were predicted to be associated with "cancer" by FATHMM." (PMID 33318575, 2020). "About 61% of ROBO1, 45% of ROBO4, and 61% of SLIT2 variants of non-lung cancer dataset were predicted to be "damaging" by SIFT." (PMID 33318575, 2020). "PolyPhen243 predicted about 15% of ROBO1, 15% of ROBO4, and 23% of SLIT2 variants of lung cancer dataset to be "possibly damaging"." (PMID 33318575, 2020). "About 89% of ROBO1, 76% of ROBO4, and 83% of SLIT2 variants of non-lung cancer dataset were predicted to cause a "decrease" in protein stability." (PMID 33318575, 2020). "The variants were analysed in PROVEAN41 that predicted nearly 50% of ROBO1, 29% of ROBO4, and 63% of SLIT2 variants of lung cancer dataset to be "deleterious"." (PMID 33318575, 2020). "In human lung cancer, low expression of Slit2 is associated with late-stage disease and poor patient survival." (PMID 24981056, 2014). "Similarly, analysis in SIFT42 revealed about 65% of ROBO1, 47% of ROBO4, and 60% of SLIT2 variants of lung cancer dataset to be "damaging"." (PMID 33318575, 2020). "This work aims at the in silico prioritisation, and pathogenicity assessment of the missense variants of SLIT2/ROBO1/4 reported in lung cancer cases, based on sequence- and structure-based parameters followed by docking analyses to determine the interaction dynamics." (PMID 33318575, 2020). "Interestingly, iMUTANT 2.0 revealed 91% of ROBO1, 79% of ROBO4, and 84% of SLIT2 variants of lung cancer dataset to cause a "decrease" in protein stability." (PMID 33318575, 2020). "Our study is the first report on the impact of cancer-associated missense variants on ROBO1/4 and SLIT2 interactions that might be the drivers of lung cancer progression." (PMID 33318575, 2020). "Our study is the first report that involves the characterisation of somatic variants of ROBO1.IG1, ROBO4.IG1-2 and SLIT2.D2 domains reported in various cancers including lung cancer, and their role in domain-domain interactions of the receptors (ROBO1.IG1 and ROBO4.IG1-2) and the ligand (SLIT2.D2)." (PMID 33318575, 2020). "Similarly, 40% of ROBO1, 18% of ROBO4, and 56% of SLIT2 variants of non-lung cancer dataset were predicted to be "deleterious" by PROVEAN." (PMID 33318575, 2020). "Levels of SLIT2 have been found to be downregulated in a majority of prostate cancers and a low level of SLIT2 has been associated with not only agressive prostate cancers, but breast and lung cancer as well." (PMID 22641253, 2012). "Finally, for the interacting domains, the prioritisation analysis revealed 2 variants of ROBO1, 2 variants of ROBO4 and 3 variants of SLIT2 in lung cancer dataset and 6 variants of ROBO1, 2 variants of ROBO4 and 15 variants of SLIT2 from the non-lung cancer dataset as depicted in." (PMID 33318575, 2020). "We identified two splicing variants of Slit2 at exon 15; Slit2-ΔE15 inhibited the proliferation and invasion/motility of CL1-5 lung cancer cells, while Slit2-WT solely inhibited invasion/motility activity." (PMID 41227302, 2025). "We identified an eight-amino acid peptide (LT1-3) within the C-terminal region of both Slit2-WT and Slit2-ΔE15, exhibiting dual functionality in inhibiting lung cancer cell proliferation and invasion." (PMID 41227302, 2025).
lung carcinoma (continued). "Both Slit2-WT and Slit2-ΔE15 inhibit lung cancer cell invasion, but Robo4 is essential for Slit2-WT-mediated invasion inhibition in CL1-5 cells, while neither Robo1 nor Robo4 is required for Slit2-ΔE15-mediated invasion inhibition." (PMID 41227302, 2025). "This study identified an 8-amino acid peptide, LT1-3, derived from the Slit2 LamG domain, and demonstrated its ability to inhibit lung cancer cell proliferation and invasion independently of Robo receptors." (PMID 41227302, 2025). "Our previous work demonstrated that Slit2-WT inhibits lung cancer cell proliferation, while Slit2-ΔE15 suppresses both proliferation and invasion." (PMID 41227302, 2025). "While Slit2/Robo plays a tumor-suppressing role in breast cancer, lung cancer, glioma, esophageal carcinoma, and colorectal cancer cells, it exhibits cancer-promoting activity in specific contexts." (PMID 41227302, 2025). "SLIT2 has previously been reported to act as a tumor-suppressor in lung cancer, thyroid cancer, gastric cancer, acute promyelocytic leukemia and other types of cancer." (PMID 38902704, 2024). "SLIT2, identified from the MSigDB database’s EMT Hallmark gene set, has been implicated as a regulator of metastasis in lung cancer, colorectal cancer, and most recently in circulating tumor cells." (PMID 38630262, 2024). "A study has shown that Slit2 dramatically reduces lung cancer cell migration, demonstrating suppression of lung cancer through Slit-Robo signaling." (PMID 38674913, 2024). "Inhibition of SLIT2 expression in endothelial cells has been shown to promote metastasis in breast and lung cancer mouse models." (PMID 37015905, 2023). "In lung cancer, SLIT2/ROBO1 suppressed cancer cell migration through regulating the Myo9b/RhoA pathway." (PMID 35615148, 2022). "For instance, in breast and lung cancer cells, Slit2 expression is frequently lost, and overexpression of Slit2 was associated with an increase in cell adhesion and a decrease in cell proliferation." (PMID 33478524, 2021). "From the non-lung cancer dataset, 113 variants of ROBO1, 134 variants of SLIT2 and 41 variants of ROBO4 were selected for structure-based analysis." (PMID 33318575, 2020). "In comparison, the other 255 variants in ROBO1, 324 variants in SLIT2 and 121 variants in ROBO4 were considered as non-lung cancer dataset." (PMID 33318575, 2020). "miR-365a-3p enhance the migration and invasion of lung cancer cells by inhibiting ubiquitin specific peptidase 33 (USP33)/ slit guidance ligand 2 (SLIT2)/ roundabout guidance Receptor 1 (ROBO1) signaling pathway." (PMID 32595638, 2020). "The cognate interaction of ROBO1/4 with its ligand SLIT2 is known to be involved in lung cancer progression." (PMID 33318575, 2020). "Out of 825 variants; 34 in ROBO1, 57 in SLIT2, and 34 in ROBO4 were reported to be associated with lung cancer." (PMID 33318575, 2020). "Recent investigations have shown the role of Myo9b-RhoA in mediating the inhibitory effect of SLIT2 on lung cancer cell migration." (PMID 33318575, 2020). "Steric clash-induced destabilisations, primarily found in variants involving bulky amino acids were 7 in ROBO1, 5 in ROBO4 and 9 in SLIT2 from the lung cancer dataset." (PMID 33318575, 2020). "The expression levels of GYPC, NME1 and SLIT2 in S30 cells and lung cancer cell lines were validated by quantitative PCR, immunofluorescence, and western blot assays." (PMID 32795291, 2020). "Slit2 was highly repressed in lung cancer specimens but showed a good expression in adjacent normal lung tissue." (PMID 30717252, 2019). "Since Slit2 expression is reduced in most inflammatory conditions, this suggests that an injection of lung cancer cells into the tail vein induces lung inflammation." (PMID 30717252, 2019). "Slit2-WT suppresses lung cancer cell invasion, while Slit2-ΔE15 inhibits both the growth and invasion of lung cancer cells." (PMID 30717252, 2019).
lung carcinoma (continued). "Due to the low expression level of Slit2 in lung cancer, in order to observe the Slit2 splicing forms in lung tumors, PCR products were precipitated from two to three PCRs and loaded onto the gel for detection." (PMID 30717252, 2019). "Lung tumors in RasG12D transgenic mice increase Slit2 expression, while an injection of lung cancer cells into the tail vein decreases Slit2 expression." (PMID 30717252, 2019). "Slit2 expression is highly repressed in lung cancer specimens when compared with their normal lung counterparts." (PMID 30717252, 2019). "We observed that Slit2-WT is predominantly expressed in both lung cancer tissue and adjacent normal lung tissue." (PMID 30717252, 2019). "In the present study, we observed that Slit2 and Robo2 mRNAs are decreased in lung cancer samples when compared to normal tissue." (PMID 31921388, 2019). "In the RT-PCR analyses, the Slit2-WT isoform was predominantly expressed in all the lung cancer specimens and in their normal lung counterparts, whereas Slit2-ΔE15 was equivalently or predominantly expressed in 41% of the pneumothorax specimens." (PMID 30717252, 2019). "An injection of lung cancer cells into the tail vein inhibited the overall expression of Slit2 in both the brain and lungs." (PMID 30717252, 2019). "USP33 deubiquitinates ROBO1 in lung cancer cells to maintain its stability, thereby regulating SLIT2 activity and inhibiting cancer cell metastasis." (PMID 29743814, 2018). "In this present study, we attempted to determine the publicly-available data from The Cancer Genome Atlas (TCGA) for comparison of miR-218 and its host gene SLIT2/3 expression levels between lung cancer tissues and normal lung tissues." (PMID 28830450, 2017). "Publicly-available data from The Cancer Genome Atlas (TCGA) was mined to compare the levels of miR-218 and its host gene SLIT2/3 between lung cancer tissues and normal lung tissues." (PMID 28830450, 2017). "In order to correlate our findings with lung cancer prognosis in clinical settings, we analyzed the data from 1405 lung cancer patients and the gene expression of miR-218 host genes (SLIT2/SLIT3), IL-6, IL-6R, JAK3 and STAT3 in their tumor tissues." (PMID 28830450, 2017). "Among the top 10 differentially expressed genes are others that are linked to pulmonary biology and/or lung cancer (SFTPB, SLIT2, TNKS)." (PMID 28445992, 2017). "In lung cancers, Slit-2 attenuation decreases cell adhesion leading to increased cell migration and metastasis." (PMID 25375180, 2014). "In our study, Slit2 significantly inhibits lung cancer cell migration, supporting that Slit-Robo signaling suppresses lung cancer." (PMID 24981056, 2014). "MiR-218, encoded on 4p15.31 and 5q35.1 within two host genes (SLIT2 and SLIT3), in a region of copy number loss, was selected as a priority candidate for follow-up as it is reported as underexpressed in lung cancer." (PMID 20838434, 2010). "SLIT2, which is a known tumor suppressor that is down-regulated in lung cancer is among these genes." (PMID 18513428, 2008). "In addition, the deletion of endothelial SLIT2 has been shown to suppress metastatic dissemination in mouse models of breast and lung cancer, while the deletion of tumoral SLIT2 enhances metastatic progression." (PMID 37443302, 2023). "SLIT2 suppresses the migration and invasion of lung cancer cells by regulating RhoA activity." (PMID 35053460, 2022). "Similarly, in the non-lung cancer dataset, 5 variants of ROBO1.IG1, 7 variants of SLIT2.D2 and 2 variants of ROBO4.IG1-2 domains show an inter-orbit shift of mutant amino acid compared to wild types." (PMID 33318575, 2020). "The details of the molecular interaction of ROBO4.IG1-2 with SLIT2.D2 in our study could provide shreds of evidence for the ROBO4 mediated angiogenesis in lung cancer pathogenesis." (PMID 33318575, 2020). "Thus, from the lung cancer dataset, 18 variants of ROBO1, 29 variants of SLIT2 and 13 variants of ROBO4 were selected for structure-based analysis." (PMID 33318575, 2020).